MMP1 (matrix metallopeptidase 1)
Diseases named in the same sentence as MMP1 in open-access papers (continued):
Sharing a sentence is not in itself a finding about the gene and the disease.
breast carcinoma (continued). "MMP1 locus was found to be hypomethylated at a promoter CpG site and its expression was upregulated in the cell line, which was verified by the drug-resistant tumor tissues from breast cancer patients (n = 28)." (PMID 35267540, 2022). "Furthermore, miR-361-5p can directly interact and bind 3′-UTR of matrix metalloproteinase-1 (MMP-1), inhibiting the invasion and metastasis of breast cancer cells." (PMID 36230935, 2022). "Moreover, abnormal overexpression of MMP1 was positively correlated with the worse outcome in breast cancer, ESCC, melanoma, colon cancer, and pancreatic carcinoma." (PMID 36105241, 2022). "Taken together, these results confirm that MMP1 is a crucial gene involved in induction of tam resistance; therefore, it could be used as a molecular target to prevent or treat tamR breast cancer." (PMID 35267540, 2022). "Furthermore, increased MMP-1 and ADAMTS-1 expressions are associated with an increased risk of bone metastasis in breast cancer patients." (PMID 36338393, 2022). "Furthermore, compared with other types of breast cancer, we noticed that triple negative breast cancer with the highest level of MMP1 expression." (PMID 36483054, 2022). "Doxorubicin at 100 nM can induce senescence in MDA-MB-231 breast cancer cells, and the SASPs of the senescent breast cancer cells include interleukin-6 (IL-6), IL-8, matrix metalloprotease-1 (MMP-1), IL-1α, and granulocyte-macrophage colony-stimulating factor (GM-CSF)." (PMID 36291773, 2022). "The results suggest that MMP-1 and MMP-3 might be associated with BC development, highlighting the need for further functional analysis of their role in breast cancer." (PMID 34445715, 2021). "Furthermore, EREG and MMP-1 overexpression increase tumor cell survival in early-stage breast cancer." (PMID 34884633, 2021). "Another study showed that silencing miR-202-3p could destroy the interendothelial junction and enhance the migration of breast cancer cells by upregulating MMP-1, suggesting that miR-202-3p/MMP-1 may be used to predict the metastasis of breast cancer." (PMID 34530822, 2021). "MMP-1 is overexpressed in breast cancer, colon cancer, and NPC." (PMID 33564686, 2021). "MMP1, the first vertebrate collagenase purified as a protein, plays a crucial role in various physiologic processes and diseases, and has been identified as a putative breast cancer marker." (PMID 33946970, 2021). "MMP1 is also upregulated to promote an invasive brain phenotype in metastatic breast cancer cells." (PMID 34445346, 2021). "However, and importantly, PBMC from both controls and breast cancer patients showed a higher MMP1 gene expression after co-culture with CAF than with normal fibroblasts, suggesting an impact on MMP1 regulation from tumor microenvironment." (PMID 33396463, 2020). "In addition, Slug enhanced MMP1 transcription by directly binding to the promoter region of breast cancer cells, resulting in multiple drug resistance." (PMID 32703314, 2020). "Interestingly, miR-101-3p upregulation reduced protein expression of COX-2 and MMP-1 in MDA231Br, which shows that restoring miR-101-3p in breast cancer cells reduces their transmigration through the brain endothelium by reducing COX-2/MMP1 expression." (PMID 32645833, 2020). "Moreover, ST08 also showed inhibition on breast cancer cell migration by inhibiting MMP1 (matrix metalloproteinase 1)." (PMID 31638975, 2019). "Matrix metalloproteinase-1 (MMP-1) is also important in breast cancer carcinogenesis." (PMID 31537868, 2019). "In addition, MMP1, the matrix metalloprotease reported to be one of the key players in breast cancer cell metastasis, was also found to be downregulated on ST08 treatment." (PMID 31638975, 2019).
breast carcinoma (continued). "In particular, metastatic breast cancer cells promote osteoclasts formation and activity by secreting osteolytic interleukins (ILs) such as IL-8 and IL-11,as well as TNFαand matrix metalloproteinases (MMP1, MMP2),which are involved in bone matrix destruction." (PMID 30126457, 2018). "Immunohistochemical analysis revealed that the breast cancer cell markers cathepsin D and MMP1 (matrix metalloproteinase 1) were highly expressed in the cocultured bone, indicating that our ex vivo metastasis model mimics the biological events triggered by cancer invasion." (PMID 30400633, 2018). "Along with the MMP1 inhibition by the RKIP/let-7/BACH1 axis in breast cancer cells, RKIP may exert inhibitory activities on MMPs expression through alternative signaling axes." (PMID 30149591, 2018). "Moreover, apelin can affect the invasion of breast cancer cells by inducing the expression of MMP-1, and in the case of gastric cancer cells, MMP-1 and MMP-9 levels were elevated." (PMID 30127323, 2018). "AHR-dependent upregulation of MMP1 may be a characteristic that breast cancer cells share with melanoma and gastric tumor cells and with TCDD-treated normal human keratinocytes." (PMID 29735912, 2018). "MMP3 and MMP1 have a synergistic effect on breast cancer carcinogenesis." (PMID 30517191, 2018). "Also of note was the significant decrease in VCAM1 (2.6-fold), TBS2 (5.2-fold), MMP1 (7.7-fold), COL14A1 (2-fold), and MMP13 (3.3-fold), all of which have been associated with breast cancer cell invasion and metastasis to bone, lung, and/or the lymphatics." (PMID 29735912, 2018). "Therefore, we infer that Slug enhances MMP1 transcription via directly binding to the promoter region in breast cancer cells, which is a previously unrecognized mechanism in the development of MDR." (PMID 28334049, 2017). "Our results indicate that miR-361-5p inhibits breast cancer cells glycolysis and invasion by respectively repressing FGFR1 and MMP-1, suggesting that miR-361-5p and its targets may serve as therapeutic targets in breast cancer treatment." (PMID 29132384, 2017). "We used Oncomine and breast cancer gene-expression miner (bc-GenExMiner) databases to assess MMP1 mRNA expression between BC cancer tissues and adjacent normal samples, and the correlations between MMP1 mRNA expression and clinicopathological characteristics." (PMID 29207651, 2017). "Then, we examined whether MMP1 expression is related to prognosis in breast cancer patients after systematic therapy (including endocrine therapy and chemotherapy) by retrieving the data in the Kaplan Meier plotter." (PMID 28334049, 2017). "The mechanism of MMP1 upregulation in breast cancer is quite complex." (PMID 28334049, 2017). "Functionally, MMP1 upregulation in breast cancer can enhance breast cancer growth and metastasis." (PMID 28334049, 2017). "Furthermore, we demonstrated that miR-361-5p inhibited breast cancer cells invasion and metastasis by targeting MMP-1." (PMID 29132384, 2017). "To address this issue, we conducted immunohistochemistry in breast cancer and adjacent normal tissues, and mined the transcriptional and survival data of MMP1 in breast cancer patients through Oncomine, Kaplan-Meier Plotter, bc-GenExMiner, COSMIC and cBioPortal databases." (PMID 29207651, 2017). "Here, we show that MMP-1 was increased in both breast cancer and dense breast tissue." (PMID 29387062, 2017). "NF-kappaB can also significantly stimulate MMP1 upregulation in breast cancer cells." (PMID 28334049, 2017). "However, the relationship between MMP1 abnormal expression and clinical outcome in breast cancer patients remains to be elucidated." (PMID 29207651, 2017). "Thus, the regulatory relationship between FGFR1 and MMP-1 downstream to miR-361-5p in breast cancer remains to be investigated in the future." (PMID 29132384, 2017).
breast carcinoma (continued). "A molecular and immunocytochemistry study carried out to assess expression of MMPs in normal breast and breast cancer cells showed that MMP-1 is predominantly found in the nuclei of tumor cells, with a small amount of cytoplasmic distribution, whereas no signal was observed in normal breast tissue." (PMID 27764205, 2016). "Earlier studies investigated the expression of MMPs in primary human breast cancer and breast cancer cell lines, concluding an enhanced expression and secretion of MMP1, -2, -3 (only in cell lines), -7 (with restriction), -10, -11, -12, -13, -14, -23, -27 and -28 in highly metastatic cell lines." (PMID 27588391, 2016). "MMP-1 was identified as a candidate gene of interest based on published studies demonstrating that MMP-1 expression is enhanced in pre-invasive lesions (ADH) that progress to invasive breast cancers." (PMID 26215578, 2015). "In addition, MMP-1 directly activates protease-activated receptors (PAR) on the breast cancer cell surface, which results in pro-invasive signals." (PMID 25664615, 2015). "MMP1 overexpression has been reported in Dox-resistant breast cancer cell line." (PMID 24804215, 2014). "Expression of MMP1 in the stromal compartment of breast carcinomas possibly represents two populations of cells: EMT transformed neoplastic cells and stromal fibroblastic cells that undergo activation of EMT induced TFs due to growth factors produced by the tumor." (PMID 24972610, 2014). "To understand how overexpression of UEV1A leads to tumorigenesis and particularly metastasis in breast cancer cells, we surveyed NF-κB and metastasis-related genes and focused on two candidate genes, MMP1 and MMP9, both of which are highly induced upon UEV1A overexpression." (PMID 25022892, 2014). "Moreover, MMP-1 in the stromal-tumor microenvironment promotes cancer invasion and angiogenesis of breast cancers through proteolytic cleavage of PAR-1 (protease-activated receptors), which is one of the proteolytically activated G-protein coupled receptors." (PMID 24531055, 2014). "MMP1 and MMP2 were associated with survival after diagnosis with breast cancer." (PMID 23696797, 2013). "Among all women combined, MMP1 and MMP2 were associated with breast cancer risk." (PMID 23696797, 2013). "Only MMP1 and MMP2 were associated with survival after diagnosis with breast cancer." (PMID 23696797, 2013). "MMP-1, -2, -3, -8 -11, and uPA have been reported to have a highly expression in breast cancer." (PMID 23844004, 2013). "Outside the clinic, MMP-1 expression has been measured in a variety of breast cancer cell lines." (PMID 25339983, 2013). "Moreover, MMP1 appears to be a key determinant that selectively mediates lung metastasis in a murine breast cancer model." (PMID 22822400, 2012). "In vitro, MMP-1 knockdown reduced the invasiveness of breast cancer cells." (PMID 23217186, 2012). "In breast cancer MMP-1 is often upregulated, especially in basal-type breast tumours." (PMID 21835023, 2011). "In addition, we wanted to correlate MMP-1 expression to breast cancer-specific survival during an extensive follow-up time." (PMID 21835023, 2011). "Few studies have correlated MMP-1 expression with breast cancer-specific survival." (PMID 21835023, 2011). "In addition, a higher content of MMP-1 and -9 protein was detected in breast cancer tissue when compared to normal breast tissue by ELISA technique." (PMID 19531263, 2009). "Nevertheless we cannot exclude that plasma MMP1 measurement in combination with assessment of other candidate or established biomarkers may improve breast cancer diagnosis." (PMID 18366705, 2008). "Our results support previous data, suggesting a tumour-promoting role for MMP1 in breast cancer." (PMID 18366705, 2008). "This high sensitivity rate suggests that plasma MMP1 may be a good candidate biomarker for breast cancer." (PMID 18366705, 2008). "We found lower plasma MMP1 levels in breast cancer patients than in healthy controls." (PMID 18366705, 2008).
breast carcinoma (continued). "In others, the MMP-1 2G/2G genotype has been associated with increased susceptibility to colorectal cancer, though not to breast cancer." (PMID 17922906, 2007). "In vivo, MMP-1 expression has been demonstrated in the stroma of nine of thirty-four breast carcinomas when examined by ISH, localised to stromal constituents during tumour formation, and to be upregulated in the stromal component of ductal carcinomas when examined by ISH and IHC." (PMID 16430785, 2006). "As MT1-MMP, MMP-1 and MMP-3 have all been implicated in the processes involved in human breast cancer, this study utilised HBC cell lines both in culture and grown as xenografts in nude mice, to investigate gene expression changes of MT1-MMP, MMP-1 and MMP-3 in vitro and in vivo using IS-RT-PCR." (PMID 16430785, 2006). "MMP-1 is expressed by the human breast cancer cells in this study and may contribute to plasmin-dependent fibrillar collagen dissolution." (PMID 15701164, 2005). "Furthermore, WISP1 appears to act as a regulator of extracellular matrix remodeling in breast cancer, broadly enhancing the expression of matrix metalloproteinases, including MMP1, MMP2, MMP9, and MT1-MMP, and shifting the MMP/TIMP balance toward a proteolytic phenotype." (PMID 41597235, 2026). "Study found that activating MMP1 expression could increases multi-drug resistance in breast cancer." (PMID 34900981, 2021). "STC1 and MMP1 have been regarded as promising markers for breast cancer; therefore, the regulation in the study, although it was in normal mammary epithelial cells, might provide reference for the targeted therapeutic treatment of breast cancer." (PMID 33946970, 2021). "Also, they inhibit migration of the cancer cells by inhibiting MMP1 in breast cancer cells." (PMID 31638975, 2019). "Moreover ADAMTS1 and MMP1 play a role in bone metastasis of breast cancer cells." (PMID 29202741, 2017). "However, the functional role of MMP1 in MDR breast cancer cells and whether other mechanisms are involved in its upregulation in the cells have not been fully understood." (PMID 28334049, 2017). "Overall, our results revealed that the polymorphisms in the promoter region of MMP1, MMP3 and MMP9 when correlated with clinicopathological characteristics and survival rate have shown significant effects on the risk and progression of breast cancer, substantiated by in-silico analysis." (PMID 28961241, 2017). "In this study, by reviewing the data in the Kaplan Meier plotter and bc-GenExMiner 4.0, we observed that high MMP1 expression is associated with significantly worse survival outcomes no matter in all breast cancer patients or only in ER+ breast cancer patients." (PMID 28334049, 2017). "Analysis of EREG and MMP-1 expression in the TCGA database did not reveal a significant association, possibly due to the fact that these samples represent invasive breast cancers, rather than early stage breast cancers." (PMID 26215578, 2015). "Besides, many other MMPs, for example MMP-1,-13, -14, may have influence on prognosis of breast cancer patients." (PMID 26270045, 2015). "Whereas MMP-13 expression (but not MMP-1 expression) was significantly and independently associated with the occurrence of distant metastasis in breast cancer, MMP-1 expression was strongly associated with the metastatic progression across the axillary lymphatic system." (PMID 25527274, 2014). "In a study with breast cancer patients with bone metastasis we showed that ICTP and MMP-1 baseline levels were associated with a shorter time to development of skeletal-related events, suggesting that MMP-1 might be useful to detect patients with tumor-induced osteolysis." (PMID 23696795, 2013). "Hence, MMP-1 knockdown reduced the proliferation of metastatic breast cancer cells in the brain." (PMID 23217186, 2012).
breast carcinoma (continued). "MMP-1 has been proposed as a biomarker for breast cancer; understanding its role in activation of the TGFα/EGFR signal pathway may lead to the use or development of additional targeted agents to suppress this axis, and result in improved treatments for metastatic breast cancer." (PMID 23217186, 2012). "The positive correlation in breast tumor and stromal cells between MMP-1 expression and several markers of tumor grade and stage provide us with some useful new insights into important questions about the molecular profiling of the stromal microenvironment in metastatic breast cancer." (PMID 21834986, 2011). "In conclusion we identified MMP-1, -2, -8, -9 -10, -11, -12, -13, -15, -19, -23, -24, -27 and -28 as matrix metalloproteinases which show a stronger expression in breast cancer tissue compared to normal breast tissue and could thus seem to be associated with breast cancer development." (PMID 19531263, 2009). "In a humanized breast cancer mouse model, LSD1 inhibition resulted in reduced FLI1 target gene signatures related to angiogenesis (VEGFA, FGF-1, MMP-1, MMP-9), migration, and invasion (PLAU)." (PMID 41300765, 2025). "We explored the effects of SPANXB1 on promoting breast cancer cell migration, invasion, VM, and BBB extravasation and further demonstrated that these effects were achieved through the upregulation of MMP1 expression." (PMID 40885703, 2025). "Single-cell analyses of breast cancer (BRCA, GSE148673) and colorectal cancer (CRC, EMTAB8107) confirmed that MMP1 expression is predominantly localized to malignant cells, macrophages, and T cells." (PMID 40394037, 2025). "ETS1 and MMP-1 are co-expressed in skin angiosarcoma, whereas ETS1 is co-expressed with MMP-1 and MMP-9 in ovarian carcinoma cells and in stromal fibroblasts of breast carcinoma." (PMID 39941022, 2025). "The inhibitory potential of rosmarinic acid on MMP-1, MMP-2, MMP-9, and MMP-12 will limiting their ability to promote proliferation, invasiveness, angiogenesis, and metastasis of breast cancer cells." (PMID 40176865, 2025). "Knockdown of MMP-1 by shRNA was reported to significantly inhibit proliferation, migration, and invasion while increasing the apoptosis of MCF-7 and MDA-MB-231 breast cancer cells." (PMID 40214422, 2025). "In summary, this study demonstrated that SPANXB1 promotes MMP1 expression and subsequently induces migration, invasion, VM formation and BBB extravasation in breast cancer cells, thus promoting BCBM progression." (PMID 40885703, 2025). "Intriguingly, breast cancer cells acquire an osteomimetic phenotype, producing osteoclastogenic cytokines such as CSF-1, PTHrP, RANKL, IL-8, IL-11, prostaglandin E, matrix metalloproteinase 1 (MMP-1), and TNF-α." (PMID 39595017, 2024). "The ECM‐related genes, including MMP1, POSTN, and FN1, have shown higher expression in breast cancer, non‐small lung cancer, bladder cancer, and gastric cancer." (PMID 38639039, 2024). "MMP-1 inhibited the invasive ability of various MDA-MB 231 cells in vitro and inhibited the growth of breast cancer cells when the cells were injected into rats." (PMID 38956273, 2024). "It has been described that sorafenib inhibits the expression of extracellular matrix proteins—MMP-1 and MMP-9—and increases the level of the adhesive protein—E-cadherin—in breast cancer cells (MCF-7 and MDA-MB-231)." (PMID 38255833, 2024). "In this situation, miR‐1246 promoted the expression of miR‐1246 precursors and MMP1, which is similar to the upregulation of GPER1 activated by miR‐339 in breast cancer." (PMID 38585233, 2024). "In conclusion, the present work demonstrates that PRDX3 plays an essential role in promoting breast cancer migration and invasion, via ERK-mediated upregulation of MMP-1." (PMID 38321552, 2024). "In this regard, administration of an ERK specific inhibitor was shown to reduce MMP-1 expression, and possibly metastasis in PRDX3-overexpressing breast cancer." (PMID 38321552, 2024).